RNU6-284P (RNA, U6 small nuclear 284, pseudogene)
Gene: Small nuclear RNA gene on chromosome 4 (164,620,732 to 164,620,837, forward strand). Ensembl gene ENSG00000223037.
Homologues: Orthologues: chimpanzee U6 (98% identical), macaque U6 (91% identical), rabbit U6 (78% identical), guinea pig U6 (73% identical). Paralogues in human: RNU6-140P (85% identical), RNU6-73P (85% identical), RNU6-946P (85% identical), RNU6-12P (84% identical), RNU6-13P (84% identical), RNU6-166P (84% identical), RNU6-25P (84% identical), RNU6-31P (84% identical), RNU6-32P (84% identical), RNU6-33P (84% identical), RNU6-41P (84% identical), RNU6-44P (84% identical), and 1288 more.